CERK (ceramide kinase)
Diseases named in the same sentence as CERK in open-access papers (continued):
Sharing a sentence is not in itself a finding about the gene and the disease.
tumor (continued). "Enhanced S1P and C1P-producing enzymes (CERK, SphK, and ATX) and activation of S1PRs in tumor tissues are closely related to poor prognostic factors that result in tumor metastasis and recurrence while attenuating chemo- and antitumor therapies, deteriorating the survival of tumor patients." (PMID 37258585, 2023). "Thus, the simultaneous increase in CHRNA7, CERK and ITGA5 expression upon the SLURP-1 treatment illustrates the activation of pro-oncogenic intracellular signaling pathways in the tumor." (PMID 37854069, 2023). "CERK expression varies significantly in both tumor and adjacent breast tissues in TNBC patients, which is consistent with the RNA-seq data for CERK in normal and tumor breast samples from The Cancer Genome Atlas." (PMID 33430896, 2021). "Since PKC-βII is a tumor suppressor, and patients with low levels of PKC-βII have a shorter survival, one might speculate that CerK is a substrate of PKC-βII, and its inactivation by phosphorylation facilitates tumor regression." (PMID 32092937, 2020). "By contrast, CerK silencing did not exert any effect on the TA of tumor-bearing mice, suggesting that the proteolytic drive in this condition already have reached the plateau and could not be further stimulated." (PMID 34209043, 2021). "However, although CerK can be a potential target to contrast tumor cell proliferation and migration in both cell subtypes, siRNA- or NVP-231-mediated CerK inhibition showed that CerK could play different roles in more aggressive metastatic BC cell lines with respect to non-metastatic cell lines." (PMID 36768427, 2023). "However, tumor cells often have relatively low levels of ceramide, due to increased activities of ceramide metabolizing enzymes such as glucosylceramide synthase (GCS), sphingomyelin synthase (SMS), ceramide kinase (CERK), acid ceramidase (AC), or sphingosine kinase (SPHK)." (PMID 31891125, 2018).
infection (2 papers, 2010 to 2024). The state of being infected such as from the introduction of a foreign agent such as serum, vaccine, antigenic substance or organism. "Collectively, these data demonstrate that CERK-derived C1P is critical for A. phagocytophilum to promote Golgi fragmentation, which, in turn, is important for it to replicate, progress through its infection cycle, and productively infect mammalian hosts." (PMID 38415594, 2024). "During this fulminant infection, absence of CERK led to drastic worsening of the disease resulting in early mortality." (PMID 20053284, 2010). "Should the T cells be polarized by CERK towards the TH2 type, the opposite hypothesis could also be considered, i.e. hyperactivation of host defenses in Cerk-/- mice might have led to poor control of the infection." (PMID 20053284, 2010).
neurodegenerative disease (2 papers, 2017 to 2022). A disorder of the central nervous system characterized by gradual and progressive loss of neural tissue and neurologic function. "In particular, it has been shown that CERK is involved in neurodegenerative diseases, inducing toxicity in rat astrocytes and neurons." (PMID 35159548, 2022).
bacterial infection (1 paper, 2011). "In this paper, we report the cloning of a ceramide kinase in rice and demonstrate that OsCERK is a bona fide ceramide kinase that can completely rescue acd5 mutant phenotypes, including spontaneous cell death, susceptibility to bacterial infection, reduced CERK activity and elevated PR1 expression." (PMID 21483860, 2011).
kidney disease (1 paper, 2025). "Together, these findings identify for the very first time CerK activity in renal BLM, establish its biochemical requirements, and highlight its potential role in modulating transporter function and sphingolipid signaling in physiology and kidney disease." (PMID 41226412, 2025).
metabolic disorders (1 paper, 2021). "Next, we asked if these data were relevant to a clinical setting, depicting the CERK-TNF-α modulations in a metabolic disorder." (PMID 33859296, 2021).
CERK also shares sentences with these, for which no sentence is quoted: Glucose intolerance (3 papers); ovarian carcinoma (2); adenocarcinoma (1); chronic kidney disease (1); colorectal carcinoma (1); epidermoid carcinoma (1); inflammatory bowel disease (1); ischemia reperfusion injury (1); Lewis lung carcinoma (1); lymph node metastasis (1); lymphedema (1); Macrocephaly (1); muscle atrophy (1); psoriasis (1); steatosis (1); type 1 diabetes (1).